TLCD2 (TLC domain containing 2)
Description:
Regulates the composition and fluidity of the plasma membrane. Inhibits the incorporation of membrane-fluidizing phospholipids containing omega-3 long-chain polyunsaturated fatty acids (LCPUFA) and thereby promotes membrane rigidity. Does not appear to have any effect on LCPUFA synthesis.
Tractability: Antibody: UniProt places it where antibodies can reach, with high confidence; its Gene Ontology location is reachable by antibodies, with high confidence; UniProt predicts a signal peptide or a membrane-spanning region.
Gene: Protein-coding gene on chromosome 17 (1,702,816 to 1,710,377, reverse strand). Ensembl gene ENSG00000185561.
Subcellular location: Cell membrane
Subcellular location (Human Protein Atlas): Vesicles
Gene Ontology:
Biological process: membrane assembly; phospholipid homeostasis; plasma membrane organization; regulation of membrane lipid distribution
Cellular component: plasma membrane; membrane
Genetic constraint (gnomAD): Loss-of-function variants: 12 observed, 14.09 expected, observed/expected ratio (o/e) 0.85, 90% interval 0.55 to 1.38. The upper end of that interval is the gene's LOEUF score, 1.38, which puts it in group 5 of 6, group 1 being the genes least tolerant of losing a copy. Missense variants: 197 observed, 186.23 expected, observed/expected ratio (o/e) 1.06, 90% interval 0.94 to 1.19. Synonymous variants: 94 observed, 84.82 expected, observed/expected ratio (o/e) 1.11, 90% interval 0.94 to 1.32.
Homologues: Orthologues: macaque TLCD2 (94% identical), chimpanzee TLCD2 (90% identical), pig TLCD2 (82% identical), rabbit TLCD2 (78% identical), dog TLCD2 (78% identical), rat Tlcd2 (73% identical), mouse Tlcd2 (72% identical), guinea pig TLCD2 (69% identical), tropical clawed frog tlcd2 (38% identical), zebrafish tlcd2 (34% identical), Caenorhabditis elegans fld-1 (30% identical), Caenorhabditis elegans K12H6.6 (27% identical), and 1 more. Paralogues in human: TLCD1 (27% identical), CLN8 (19% identical), TLCD4 (16% identical), TLCD3A (15% identical), TLCD3B (13% identical).
Diseases named in the same sentence as TLCD2 in open-access papers:
TLCD2 is named in the same sentence as 6 diseases in open-access papers, as found by Europe PMC text mining. Sharing a sentence is not in itself a finding about the gene and the disease. The quoted sentences say what the papers report.
cardiac hypertrophy (3 papers, 2013 to 2022). "TLCD2 participates in Chromosome 17P13.3, Centromeric, Duplication Syndrome and is reported to be associated with increased left ventricular mass and cardiac hypertrophy." (PMID 35990977, 2022). "TLCD2 has been hypothesised to be involved in ceramide synthesis and lipid metabolism, which has been associated with cardiac metabolism and may contribute towards cardiac hypertrophy." (PMID 23372812, 2013).
liver disease (1 paper, 2022). "It will be of interest to investigate TLCD1 and TLCD2 individually in the future to understand the differences in their mechanism of action, and their relative contributions to the liver disease phenotypes observed in the Tlcd1/2 DKO mice in this study." (PMID 36241646, 2022).
melanoma (1 paper, 2025). A malignant, usually aggressive tumor composed of atypical, neoplastic melanocytes. "Analysis of differential MEs revealed module 14 (TLCD2, PRICKLE2-AS3, and SPN) was significantly upregulated by NRAS Q61L melanomas (log2fc = 100.2, adjusted p = 1.32 × 10−2) and downregulated by BRAF V600E melanomas (log2fc = −206.3, adjusted p = 3.51 × 10−14)." (PMID 39796775, 2025).
non-alcoholic steatohepatitis (1 paper, 2022). "Here, the authors show that TLCD1 and TLCD2 proteins mediate the formation of monounsaturated fatty acid-containing PE species and promote the progression of non-alcoholic steatohepatitis." (PMID 36241646, 2022).
renal carcinoma (1 paper, 2019). A carcinoma arising from the epithelium of the renal parenchyma or the renal pelvis. "For example, renal cancer patients with higher TLCD2 expression were found to have worse survival time (Atlas); upregulated SPN expression was found to associate with better survival in endometrial, breast and melanoma cancers (Atlas)." (PMID 30949194, 2019).
type 2 diabetes (1 paper, 2024). "The top suggestive associations in early (POU5F1-whole blood), late (CADM1-breast), and total (TLCD2-subcutaneous adipose) GWG using maternal genotypes have also been tied to related traits, including BMI, BMI-adjusted hip circumference, type 2 diabetes, and waist to hip ratio." (PMID 38854080, 2024).